TACC3 (transforming acidic coiled-coil containing protein 3)
Description:
Plays a role in the microtubule-dependent coupling of the nucleus and the centrosome. Involved in the processes that regulate centrosome-mediated interkinetic nuclear migration (INM) of neural progenitors (By similarity). Acts as a component of the TACC3/ch-TOG/clathrin complex proposed to contribute to stabilization of kinetochore fibers of the mitotic spindle by acting as inter-microtubule bridge. The TACC3/ch-TOG/clathrin complex is required for the maintenance of kinetochore fiber tension. May be involved in the control of cell growth and differentiation. May contribute to cancer.
Synonyms: ERIC1; ERIC-1; maskin; Tacc4
Tractability: Small molecule: a structure with a bound ligand is known. PROTAC: it is named in the literature on targeted protein degradation; ubiquitination databases record sites on it; its protein half-life has been measured.
Chemical probes: BO-264 (high quality)
Gene: Protein-coding gene on chromosome 4 (1,712,858 to 1,745,178, forward strand). Ensembl gene ENSG00000013810.
Subcellular location: Cytoplasm; Cytoplasm, cytoskeleton, microtubule organizing center, centrosome; Cytoplasm, cytoskeleton, spindle; Cytoplasm, cytoskeleton, spindle pole
Subcellular location (Human Protein Atlas): Centriolar satellite; Cytosol; Basal body; Golgi apparatus; Mitotic spindle
Pathways (Reactome):
Signal Transduction: NOTCH3 Activation and Transmission of Signal to the Nucleus; Negative regulation of NOTCH4 signaling
Gene Ontology:
Molecular function: protein binding
Biological process: metaphase/anaphase transition of mitotic cell cycle; microtubule cytoskeleton organization involved in mitosis; regulation of mitotic spindle organization; astral microtubule organization; cerebral cortex development; chromosome segregation; mitotic cell cycle; mitotic spindle organization; nuclear migration
Cellular component: centriolar satellite; ciliary basal body; centrosome; cytosol; kinetochore microtubule; mitotic spindle microtubule; cytoplasm; spindle; spindle pole
Genetic constraint (gnomAD): Loss-of-function variants: 52 observed, 85.77 expected, observed/expected ratio (o/e) 0.61, 90% interval 0.48 to 0.76. The upper end of that interval is the gene's LOEUF score, 0.76, which puts it in group 3 of 6, group 1 being the genes least tolerant of losing a copy. Missense variants: 1,120 observed, 1,097.8 expected, observed/expected ratio (o/e) 1.02, 90% interval 0.97 to 1.07. Synonymous variants: 512 observed, 440.78 expected, observed/expected ratio (o/e) 1.16, 90% interval 1.08 to 1.25.
Homologues: Orthologues: chimpanzee TACC3 (99% identical), macaque TACC3 (89% identical), dog TACC3 (58% identical), guinea pig TACC3 (52% identical), rat Tacc3 (47% identical), mouse Tacc3 (38% identical), tropical clawed frog tacc3 (37% identical), zebrafish tacc3 (28% identical), Drosophila melanogaster tacc (19% identical). Paralogues in human: TACC2 (28% identical), TACC1 (20% identical).
Diseases named in the same sentence as TACC3 in open-access papers:
TACC3 is named in the same sentence as 116 diseases in open-access papers, as found by Europe PMC text mining. Sharing a sentence is not in itself a finding about the gene and the disease. The quoted sentences say what the papers report.
glioblastoma (86 papers, 2010 to 2026). The most malignant astrocytic tumor (WHO grade IV). "Two fusions identified as having oncogenic potential in our study had previously been associated with glioblastoma: FGFR3::TACC3 and EGFR::SEPTIN14." (PMID 36002559, 2022). "The essential mammalian gene TACC3 is frequently mutated and amplified in cancers and its fusion products exhibit oncogenic activity in glioblastomas." (PMID 26134678, 2015). "Two fusions had previously been associated with glioblastoma: FGFR3::TACC3 and EGFR::SEPTIN14." (PMID 36002559, 2022). "TACC3 is a tumor-associated protein that has been found to play critical roles in the development of various cancer types, such as ovarian cancer, hepatocellular carcinoma, glioblastoma, and so on." (PMID 34160364, 2021). "Furthermore, a TACC3 somatic mutation (p.E680K) was reported in one of 22 glioblastomas." (PMID 21113414, 2010). "Diffuse gliomas with FGFR3::TACC3 fusion constitute a distinct molecular subtype with potentially unique radiological features, particularly prominent calcifications with an infiltrative tumor growth pattern suggestive of glioblastoma, IDH-wildtype, which may serve as a useful diagnostic marker." (PMID 40417325, 2025). "Here, we report a case of diffuse glioma with FGFR3::TACC3 fusion, characterized by striking calcifications and a diffuse infiltrative growth pattern consistent with glioblastoma, IDH-wildtype." (PMID 40417325, 2025). "Diffuse gliomas with FGFR3::TACC3 fusion (F3T3 gliomas) and high-grade histological features harbor molecular stigmata and the DNA methylation profile of glioblastoma, though they are associated with slightly longer patient survival." (PMID 38730596, 2024). "The FGFR3::TACC3 fusion was detected in one out of 72 samples of glioblastoma in the Ivy Center cohort, and 2 of 161 samples in the TCGA cohort." (PMID 39087020, 2024). "In glioblastoma, a series of analogs of KHS101 have been shown to have significant anti-tumor cell proliferation activity by inhibiting TACC3 functions and are expected to be developed for the treatment of glioblastoma." (PMID 38012214, 2023). "Gliomas with FGFR3::TACC3 fusion mainly occur in adults, display pathological features of glioblastomas (GB) and are usually classified as glioblastoma, IDH-wildtype." (PMID 36647073, 2023). "The FGFR3-TACC3 fusion protein has been identified with differing exonic breakpoints within TACC3 in numerous cancers including glioblastoma, bladder cancer, lung adenocarcinoma, and head and neck squamous cell carcinoma." (PMID 36780330, 2023). "In 2012, whole-transcriptome sequencing analysis led to the discovery of recurrent fusions involving the FGFR3 and TACC3 genes as the main oncological driver in a subset of human glioblastomas." (PMID 38067258, 2023). "As the result of an intrachromosomal translocation on human chromosome 4p16, FGFR3-TACC3 was first discovered in glioblastoma with TACC3 fused to a slightly truncated FGFR3 with an intact kinase domain." (PMID 36780330, 2023). "Diffuse gliomas with FGFR3::TACC3 fusion have been mainly reported in the adult setting where they account for 3.1–11.8% of cases with pathological features of glioblastoma." (PMID 36647073, 2023). "Glioblastomas with FGFR3::TACC3 fusion are mainly distributed between mesenchymal and RTK2 MC subtypes." (PMID 36647073, 2023). "The first gene fusion discovered was between FGFR3 and the transforming acidic coiled-coil containing protein (TACC3) forming FGFR3-TACC3 in glioblastoma." (PMID 34867402, 2021). "Metabolic rewiring as occurs in IDH1mt glioblastoma has also been described as occurring in 3% of glioblastoma patients with fibroblast growth factor receptor 3 (FGFR3)–transforming acidic coiled-coil-containing protein 3 (TACC3) gene fusions." (PMID 33810170, 2021). "The most common FGFR3 fusions are with the transforming acidic coiled-coil containing protein 3 (TACC3) and have been discovered in glioblastoma, bladder cancer, and lung cancer." (PMID 34272467, 2021).
glioblastoma (continued). "Fibroblast growth factor receptor 3 (FGFR3)-transforming, acidic coiled-coil containing protein 3 (TACC3) in glioblastoma and chromosome 2 open reading frame 14 (C2orf44)-ALK fusions in colorectal cancer are examples of tandem duplications." (PMID 31007851, 2019). "High TACC3 expression has been detected in ovarian cancer, glioblastoma, esophageal squamous cell carcinoma, and colorectal cancer." (PMID 30341253, 2018). "Intriguingly, oncogenic fusion products between FGFR3 and TACC3 have been identified in glioblastoma, bladder, lung, and nasopharyngeal carcinomas." (PMID 29358577, 2018). "In particular, FGFR-TACC fusions which is clonal tumor-initiating events appear in 3% of glioblastoma for FGFR3- TACC3 fusion, confer strong sensitivity to FGFR tyrosine kinase in preclinical and preliminary clinical data." (PMID 30167084, 2018). "TACC3 has also been found as a gene fusion product with the cytoplasmic domain of the fibroblast growth factor receptor (FGFR) in glioblastoma multiforme and lung cancer." (PMID 27956147, 2017). "For instance, there are reports that upregulated TACC3 was detected in glioblastoma, non-small-cell lung cancer, non-Hodgkin's lymphoma, and multiple myeloma patients." (PMID 28655970, 2017). "TACC3 is also involved in the development of glioblastoma, multiple myeloma, lung cancer and breast cancer, while TACC3 expression is decreased in thyroid and ovarian cancers." (PMID 27705912, 2016). "FGFR3 fusion with TACC3 has been reported to have transforming effects in primary glioblastoma and display oncogenic activity in vitro and in vivo." (PMID 27829236, 2016). "Recently, FGFR3-transforming acidic coiled-coil 3 (TACC3) fusions have been identified in glioblastoma, head and neck carcinoma, and lung cancer, as well as urothelial cancer (UC)." (PMID 27930669, 2016). "A Q-PCR analysis of an independent panel of glioblastoma samples detected genomic duplications of TACC3 in 5 out of 101 samples." (PMID 21113414, 2010). "Using an integrative genomic strategy, we have analyzed genes altered in the 4p16.3 region in glioblastomas and revealed that TACC3 is the primary glioblastoma-targeted gene in this region." (PMID 21113414, 2010). "We found that ERRFI1 is a potential glioblastoma-targeted tumor suppressor gene and TACC3 is a potential oncogene." (PMID 21113414, 2010). "We further demonstrated that ERRFI1 and TACC3 in 1p36.23 and 4p16.3, respectively, are potential glioblastoma-targeted genes." (PMID 21113414, 2010). "In addition to various mutations and amplifications in the gene, oncogenic fusion products between FGFR3 and TACC3 have been identified in glioblastoma, bladder, lung and nasopharyngeal carcinomas." (PMID 26134678, 2015). "Studies have shown that up-regulation of TACC3 is found in glioblastoma, non-small cell lung cancer (NSCLC) and multiple myeloma and may contribute to lymphomagenesis." (PMID 23936413, 2013). "Therefore, to determine the correlation of TACC3 and Aurora kinase expression, we used Serial Analysis of Gene Expression (SAGE) and TCGA expression data sets to evaluate TACC3 and Aurora kinase gene expression in glioblastomas." (PMID 21113414, 2010). "Furthermore, we demonstrate that TACC3, an Aurora-A kinase substrate, on 4p16.3, displays gain of copy number, is overexpressed in a glioma-grade-specific pattern, and correlates with Aurora kinase overexpression in glioblastomas." (PMID 21113414, 2010). "FGFR3::TACC3 fusion-positive gliomas demonstrate a relatively favorable prognosis, with better outcomes than FGFR3::TACC3-negative glioblastomas, although still poorer than those of IDH-mutant gliomas." (PMID 40417325, 2025). "Histopathological examination confirmed glioblastoma, IDH-wildtype, and subsequent genetic testing revealed FGFR3::TACC3 fusion and amplification of FGFR3 gene." (PMID 40417325, 2025).
glioblastoma (continued). "But we have to keep in mind that among glioblastoma, IDH-wildtype, those that harbor FGFR3::TACC3 fusion display a better prognosis than the others." (PMID 36647073, 2023). "In contrast, the FGFR3-TACC3 fusion has been described at low frequencies (2–8%) in urothelial cancers and glioblastoma and mediates it oncogenic activity through constitutive dimerization of FGFR3 driven by TACC3." (PMID 32370101, 2020). "A recent study also demonstrated that a small-molecule inhibitor of transforming acidic coiled-coil containing protein 3, KHS101, effectively kills glioblastoma cells in vitro and in vivo by impairing mitochondrial metabolism and ATP production." (PMID 30717309, 2019). "TACC3 levels are altered in several human cancers, for example, ovarian, non-small cell lung cancer, and bladder, and fusions between TACC3 and FGFR3 are reported in glioblastoma and bladder cancer." (PMID 26090906, 2015). "Our multifaceted genomic evaluation of glioblastoma establishes ERRFI1 as a potential candidate tumor suppressor gene and TACC3 as a potential oncogene, and provides insight on targets for oncogenic pathway-based therapy." (PMID 21113414, 2010). "Considering the presence of calcifications, differential diagnoses include FGFR3::TACC3 fusion-negative glioblastoma, oligodendroglioma, ependymoma, ganglioglioma, and polymorphous low-grade neuroepithelial tumors of the young (PLNTY)." (PMID 40417325, 2025). "Diffuse gliomas with FGFR3::TACC3 fusion have an intermediate prognosis, with poorer survival outcomes than IDH-mutant gliomas but superior outcomes compared to FGFR3::TACC3-negative glioblastomas." (PMID 40417325, 2025). "Patients with FGFR3::TACC3 fusion-positive glioblastomas were reported to be similar in age or slightly older at diagnosis compared to those with fusion-negative glioblastomas, with variable reports regarding sex predominance." (PMID 40417325, 2025). "In glioblastoma, the fusion of FGFR3 with transforming acidic coiled-coil containing protein (TACC3) results in FGFR3-TACC3, which activates MAPK and extracellular signal-regulated kinase (ERK) signaling, facilitates in vitro transformation and increases cell proliferation." (PMID 38686058, 2024). "For example, in glioblastoma, the FGFR3 (fibroblast growth factor receptor 3) gene has been shown to escape regulation by the miR-99a microRNA due to a fusion with the 3’UTR of the TACC3 (transforming, acidic coiled-coil containing) gene." (PMID 28851357, 2017). "While the mechanism for their co-expression with the ones on cytoband 4p1 is not clear, literature review shows that the gene TACC3 in Module 66 on cytoband 4p16 is known to have a gene fusion with FGFR1 gene in 3 % of glioblastoma multiforme patients." (PMID 27556416, 2016). "Interestingly, TACC3 has been identified as a fusion partner to FGFR3 in bladder cancer, squamous cell lung cancer, oral cancer, head and neck cancer and glioblastoma multiforme." (PMID 24550739, 2014). "In a recent study, the median overall survival of FGFR3::TACC3 fusion-positive glioblastomas was reported to be 31.1 months, significantly longer than that of fusion-negative glioblastomas (19.9 months), with the fusion serving as an independent predictor of better outcome." (PMID 40417325, 2025). "Histopathologically, diffuse gliomas with FGFR3::TACC3 fusion frequently exhibit microcalcifications, nuclear palisading, and curvilinear capillary proliferation, which have been reported to be significantly more prominent than those in FGFR3::TACC3-negative glioblastomas." (PMID 40417325, 2025).
glioblastoma (continued). "FGFR3 fusion with transforming acidic coiled-coil-containing protein 3 (TACC3) (FGFR-TACC3) has been characterized and correlated with a more aggressive phenotype in malignancies such as glioblastoma and head and neck cancers, for which no effective therapeutic option is still available." (PMID 37715207, 2023). "Scientific evidence reveals that human glioblastoma is also characterized by oncogenic fusions involving the members of the FGFR3 and FGFR1 tyrosine kinases (TKs) to the transforming acidic coiled-coil (TACC) proteins, in particular TACC3 and TACC1, necessary to promote cell division." (PMID 33352931, 2020). "Notably, coarse calcifications in the deep white matter have emerged as a distinctive radiological feature that may aid in differentiating diffuse gliomas with FGFR3::TACC3 fusion from fusion-negative glioblastomas." (PMID 40417325, 2025). "Further studies are needed to compare the frequency and distribution of calcifications in FGFR3::TACC3 fusion-positive and -negative IDH-wildtype glioblastomas." (PMID 40417325, 2025). "Interestingly, a previous study identified among 79 glioblastomas with FGFR3::TACC3 fusion 11 cases that formed on t-SNE analysis a separate cluster (named ‘outlier’ FGFR3::TACC3 positive glioblastoma, GBM-F3T3-O) close to the cluster of GBM-mesenchymal subtype." (PMID 36647073, 2023). "In adult setting, patients suffering from a glioblastoma, IDH-wildtype harboring FGFR3::TACC3 fusions have a better survival rate than cases without FGFR3::TACC3 fusion." (PMID 36647073, 2023).